TRPM7 (transient receptor potential cation channel subfamily M member 7)
Diseases named in the same sentence as TRPM7 in open-access papers (continued):
Sharing a sentence is not in itself a finding about the gene and the disease.
endotoxemia (4 papers, 2014 to 2024). "Endotoxemic rats showed that TRPM7 promotes a procoagulant phenotype and increases death and the relative risk of death, since TRPM7 downregulation protects against those endotoxemia-mediated features." (PMID 36869357, 2023). "Furthermore, increased TRPM7 expression was shown to be associated with liver and kidney failure as a mechanism for endotoxemia-mediated death." (PMID 36869357, 2023). "Interestingly, the increased plasma levels of AST, ALT and TBIL in endotoxin-treated AdVCTRL-infected rats correlated with TRPM7 mRNA and protein expression (E and G respectively), supporting the notion that TRPM7 is associated with endotoxemia-induced liver failure." (PMID 36869357, 2023). "Here, we showed that the procoagulant phenotype during endotoxemia is mediated by TRPM7 ion channel and α-kinase activity in ECs, which promotes liver and kidney failure and increases both death and the relative risk of death." (PMID 36869357, 2023). "TRPM7 plays a salient role in macrophage activation in response to inflammatory stimuli, and accordingly, when Trpm7 is deleted selectively in myeloid cells, the mice are highly resistant to endotoxemia." (PMID 37943249, 2024). "Thus, loss-of-function experiments were performed to analyze the role played by TRPM7 in regulating the procoagulant phenotype during endotoxemia." (PMID 36869357, 2023). "Considering that endotoxemic challenge induces mortality and that endotoxemia-induced endothelial TRPM7 expression increases, we were prompted to determine whether TRPM7 expression suppression protects against endotoxemia." (PMID 36869357, 2023). "Therefore, the aim of this study was to examine if the TRPM7 channel mediates coagulation during endotoxemia." (PMID 36869357, 2023). "Then, the participation of TRPM7 in the procoagulant phenotype during endotoxemia was investigated." (PMID 36869357, 2023). "Additionally, we demonstrated that TRPM7 expression and activity are related to renal vascular hyperpermeability, kidney dysfunction and increased mortality in rats with endotoxemia." (PMID 33291725, 2020). "We recently demonstrated that the role of TRPM7 in the progression of endotoxemia is that the channel expression and activity increase the secretion of pro-inflammatory cytokines like tumor necrosis factor-a (TNF-α), IL-1β, IL-6 and IL-12 without changing the anti-inflammatory cytokine production." (PMID 33291725, 2020). "The fact that inhibition of the TRPM7 channel abolished the endotoxin-induced increase in ECM expression in ECs indicates that this channel is a key protein involved in the progression of endothelial fibrosis under endotoxemia-like conditions." (PMID 24710004, 2014). "Thus, TRPM7 emerges as a novel target for drug design to improve current treatments against endotoxemia-derived sepsis syndrome and further inflammatory diseases." (PMID 24710004, 2014). "Therefore, our aim was to examine if TRPM7 mediates coagulation during endotoxemia." (PMID 36869357, 2023). "Notably, the endotoxemia-induced increases in the AKI markers KIM-1, NGAL and β2M were inhibited by TRPM7 suppression." (PMID 36869357, 2023).
gastric adenocarcinoma (4 papers, 2018 to 2024). "A ginsenoside and some plant extracts from Korea and China have been reported to induce apoptosis, inhibit cell growth and survival by blocking TRPM7 proteins in human gastric adenocarcinoma cells." (PMID 38255793, 2024). "Human gastric adenocarcinoma cells have been shown to express TRPM7 channels that are possibly involved in the growth and survival of tumor cells." (PMID 38255793, 2024). "TRPM7 channels have been shown to be predominant actors in the growth and survival of human gastric adenocarcinoma cells." (PMID 29875336, 2018).
Hypocalcemia (4 papers, 2020 to 2025). An abnormally decreased calcium concentration in the blood. "In individuals with variants in TRPM6 and TRPM7, encoding Mg2+ channels crucial for uptake of Mg2+ in the DCT and other tissues, it has been shown that hypocalcaemia can occur secondary to hypomagnesaemia." (PMID 38519529, 2024). "The top four research frontiers of TRPM7 were ion channel, magnesium, secondary hypocalcemia (HSH), and proliferation." (PMID 32643506, 2020). "Albeit that we found a pivotal evidence of TRPM7’s involvement in secondary hypocalcemia, researchers still need to further clarify the therapeutic approaches of secondary hypocalcemia." (PMID 32643506, 2020). "Although there is no research data verifying that TRPM7 is directly related to secondary hypocalcemia, the proteins of TRPM6 and TRPM7 have a high sequence similarity and the TRPM6/TRPM7 hetero-oligomerization plays a role in TRPM6-mediated epithelial magnesium absorption." (PMID 32643506, 2020).
inflammatory bowel disease (4 papers, 2020 to 2025). A spectrum of small and large bowel inflammatory diseases of unknown etiology. "TRPM7 was overexpressed in human inflammatory bowel disease-related and sporadic CRC, and it had positive correlation to tumor grade." (PMID 36363540, 2022). "The search terms used were "Transient Receptor Potential Channels", "TRP channels", "TRPV1", "TRPA1", "TRPV4", "TRPV2", "TRPM2", "TRPM3", "TRPM7", "TRPM8", "TRPC3", "colitis", "inflammatory bowel disease", "IBD", "ulcerative colitis", "Crohn Disease"." (PMID 41096659, 2025).
lymph node metastasis (4 papers, 2018 to 2022). "In the Lumina B subtype, we similarly found that TRPM7 methylation was negatively associated with lymph node metastasis and radiotherapy, while positively associated with endocrine therapy." (PMID 36064388, 2022). "TRPM7 methylation was negatively associated with lymph node metastasis and radiotherapy in patients with Her2 positive and Lumina A subtypes." (PMID 36064388, 2022). "The univariate analyses showed that TRPM7 methylation status was significantly associated with molecular subtypes (OR = 1.27; 95% CI = 1.00–1.63; P = 0.05), lymph node metastasis (OR = 0.09; 95% CI = 0.04–0.22; P = 0.001), and radiotherapy (OR = 0.37; 95% CI = 0.21–0.64; P = 0.001)." (PMID 36064388, 2022). "Next, we further examined the relationship of TRPM7 methylation with clinicopathological characteristics, and found that TRPM7methylation was found to be significantly associated with molecular subtypes, lymph node metastasis, disease recurrence and cancer related death." (PMID 36064388, 2022). "This is corroborated by findings of our clinicopathological analysis showing that high TRPM7 expression positively correlates with lymph node metastasis (p = 0.005)." (PMID 30477473, 2018). "Moreover, we also found methylation frequency of TRPM7 was negatively correlated with lymph node metastasis, disease recurrence and cancer related death." (PMID 36064388, 2022).
Macrothrombocytopenia (4 papers, 2016 to 2025). "Members of a human pedigree with mutations in TRPM7 (p.C721G), causing disrupted channel activity, suffer from macrothrombocytopenia and arterial fibrosis." (PMID 30126133, 2018). "Collectively, our findings reveal TRPM7 dysfunction as a novel cause of macrothrombocytopenia in mice and potentially in humans too." (PMID 27020697, 2016). "In the present study, we provide evidence that defects in TRPM7 channel function cause macrothrombocytopenia in mice and likely in humans too." (PMID 27020697, 2016). "However, the impaired channel activity and the striking phenotypic similarities in platelets from patients and Trpm7fl/fl-Pf4Cre mice strongly suggest that the variants in TRPM7 account for the observed macrothrombocytopenia." (PMID 27020697, 2016). "We next hypothesized that some DNA variants of extreme low-frequency affecting TRPM7 channel function might also cause macrothrombocytopenia in humans." (PMID 27020697, 2016). "Collectively, our findings reveal that TRPM7 dysfunction may cause macrothrombocytopenia in humans and mice." (PMID 27020697, 2016). "Notably, a mouse strain with conditional megakaryocyte-restricted Trpm7 KO also developed macrothrombocytopenia." (PMID 41118703, 2025). "Sanger sequencing showed that the p.C721G variant was present in two further pedigree members with macrothrombocytopenia, but was absent in one asymptomatic pedigree member, indicating segregation with the TRPM7 genotype." (PMID 27020697, 2016). "Furthermore, impaired channel activity of TRPM7 induces macrothrombocytopenia in mice and humans, implicating that long-term inhibition of TRPM7 channel activity in disease condition may alter platelet biogenesis and function." (PMID 31652790, 2019). "In contrast, homozygous kinase-dead TRPM7R/R mice show normal platelet counts, size and morphology, thus suggesting that the lack of TRPM7 channel rather than its kinase activity accounts for the macrothrombocytopenia in Trpm7fl/fl-Pf4Cre mice." (PMID 30126133, 2018). "Furthermore, Trpm7+/− mice did not display macrothrombocytopenia suggesting that gene haploinsufficiency does not account for the observed disease." (PMID 27020697, 2016).
multiple sclerosis (4 papers, 2019 to 2024). A progressive autoimmune disorder affecting the central nervous system resulting in demyelination. "FTY720, an FDA-approved drug for multiple sclerosis inhibits TRPM7." (PMID 37943249, 2024). "TRPM7 is overexpressed in astrocytes isolated from patients with multiple sclerosis, and this dysregulation seems to be involved in the early and late steps of multiple sclerosis." (PMID 36613667, 2022). "This study took advantage of the earlier finding that FTY720, an FDA-approved drug that targets S1P1 for the treatment of multiple sclerosis, inhibits TRPM7 in its unphosphorylated prodrug form, but not in its phosphorylated form." (PMID 37943249, 2024). "Moreover, in multiple sclerosis (MS), transient receptor potential cation channel, subfamily M, member 7 (TRPM7, a Ca2+-permeable nonselective cation channel) was highly expressed in RAs to mediate CSPGs production." (PMID 37307832, 2024).
pulmonary hypertension (4 papers, 2019 to 2021). Increased pressure within the pulmonary circulation due to lung or heart disorder. "TRPM7 deletion attenuates the signs of pulmonary hypertension in MCTp-induced PH mouse." (PMID 33691194, 2021). "Our findings therefore strongly suggest a crucial role of TRPM7 in the development of experimental pulmonary hypertension and that OCS exhibited therapeutic effects by inhibiting the TRPM7 activity." (PMID 33691194, 2021).
Thrombocytopenia (4 papers, 2018 to 2024). A reduction in the number of circulating thrombocytes. "It is important to mentioned that, in MAGT1-deficient cells, Mg2+ supplementation increased the free intracellular Mg2+ levels, most likely through TRPM7 (Transient receptor potential cation channel subfamily M member 7), which molecular alteration has been related to thrombocytopenia." (PMID 36982178, 2023).
adenoma (3 papers, 2014 to 2025). A neoplasm arising from the epithelium. "- TRPM7 (Thr1482Ile) polymorphism associated with elevated risk of both adenomatous and hyperplastic polyps. - Individuals with TRPM7 (Thr1482Ile) polymorphism with a high Ca:Mg ratio intake in diet at a relatively high risk of developing adenoma and hyperplastic polyps." (PMID 25079291, 2014). "In a recent report, expression levels of cyclooxygenase (COX)-2, particularly COX-2 combined with TRPM7 and MLKL, in rectal mucosa were longitudinally associated with increased risks of metachronous adenomas and serrated polyps." (PMID 40750038, 2025).
asthma (3 papers, 2010 to 2022). "In most of the cells, TRP channels are expressed, and strong evidence for an essential role in airway function and associated diseases, such as CF, asthma, fibrosis and edema was demonstrated for TRPA1, TRPC6, TRPM2, TRPM5, TRPM7, TRPV2, TRPV4 and TRPV6." (PMID 36139480, 2022). "However, our findings suggest that TRPM7 is an important channel and may serve as a potential target for immunotherapy in asthma." (PMID 24995695, 2014). "Moreover, another 5-LOX specific inhibitor, zileuton, an oral drug for asthma, did not block TRPM7 channel activity within the time-course of our electrophysiological recordings." (PMID 20567598, 2010).
atherosclerosis (3 papers, 2023 to 2024). A disease characterized by the build-up of fatty material and calcium deposition in the arterial wall resulting in partial or complete occlusion of the arterial lumen. "In conclusion, their study suggested that the circ_0021155/miR-4459/TRPM7 axis regulated the phenotypic transformation of VSMCs in atherosclerosis." (PMID 37103045, 2023). "They found that circ_0021155 was related to transient receptor potential cation channel subfamily m member 7 (TRPM7), which regulates the proliferation and migration of VSMCs in atherosclerosis." (PMID 37103045, 2023). "The increase in MEK/ERK phosphorylation caused by the ox LDL activation of TRPM7 may mediate the proliferation and migration of VSMC, suggesting that blocking TRPM7 may have potential in treating atherosclerosis." (PMID 38255767, 2024).
basophilic leukemia (3 papers, 2014 to 2015). "- Waixenicin inhibits and T cell leukemia (Jurkat T lymphocytes) and rat basophilic leukemia cells (RBL1) through blocking TRPM7 channel activity." (PMID 25079291, 2014). "Extracellular spermine blocked endogenous TRPM7 currents in rat basophilic leukemia (RBL) cells with an IC50 value of 2.3 μM, and 20 μM SKF-96365 was sufficient for complete inactivation of TRPM7 in RBL cells." (PMID 25437439, 2014). "In addition, TRP currents including TRPV5 and TRPM7 are reduced by intracellular Mg2+ as well as other divalent such as Ba2+, Sr2+, Mn2+, and Zn2+ through charge shielding of PIP2 by cations in rat basophilic leukemia and T-lymphocyte and in heterologous expression systems." (PMID 26658739, 2015).
brain injury (3 papers, 2015 to 2024). Acute and chronic (see also brain INJURIES, CHRONIC) injuries to the brain, including the cerebral hemispheres, CEREBELLUM, and brain STEM. "This suggests that TRPM7 is relevant to HI-induced brain injury and can potentially serve as a therapeutic target for hypoxic-ischemic brain injury, the function of which can be modulated by carvacrol." (PMID 25761704, 2015). "Furthermore, activation of the RIP3/MLKL/TRPM7 pathway also worsens inflammation in brain tissue of rats suffering from traumatic brain injury." (PMID 39329120, 2024). "It suggests that carvacrol blocks TRPM7 function partly by reducing its enzyme substrate, m-calpain, to restore Bcl-2 expression leading to prevention of apoptosis in neonatal hypoxic-ischemic brain injury." (PMID 25761704, 2015). "This indicates that the TRPM7 channel may be involved in neonatal hypoxic-ischemic brain injury." (PMID 25761704, 2015). "This study’s use of a pre-treatment paradigm provides “Proof of Principle” for: 1) the involvement of a non-glutamatergic mechanism (TRPM7) in HI brain injury, and 2) the idea that TRPM7 blockers (i.e. carvacrol) are a promising target for drug development against HI-induced brain injury." (PMID 25761704, 2015).
breast adenocarcinoma (3 papers, 2021). "TRPM7 is overexpressed in human breast adenocarcinoma tissue, whereas TRPM7 silencing attenuates MCF-7 cell proliferation." (PMID 33806911, 2021). "Waixenicin A, a natural terpenoid, has been identified as an efficient suppresser of TRPM7 and shows deleterious effects on the malignant behaviors of human gastric and breast adenocarcinoma cells." (PMID 34285910, 2021). "Within MDA-MB-231 breast adenocarcinoma and HT1080 fibrosarcoma cells, TRPM7 acts as a mechanosensor of hydraulic resistance, which drives Ca2+ influx; a function which is abolished by TRPM7 inhibition or functional TRPM7 KO." (PMID 33922466, 2021).
chronic pancreatitis (3 papers, 2015 to 2022). A chronic inflammatory process causing damage and fibrosis of the pancreatic parenchyma. "In chronic pancreatitis, pre-malignant tissues, and malignant neoplasms, there is variable expression of TRPM7." (PMID 25770184, 2015). "In chronic pancreatitis, the expression level of TRPM7 is relatively high; anti-TRPM7 immunoreactivity in the cytoplasm of the pancreatic ductal and acinar cells is readily detectable." (PMID 25770184, 2015). "In this chronic pancreatitis model, expression of TRPM7 was also increased at the protein level." (PMID 35883700, 2022). "Since TRPM7 expression was also in line with the activation status of another cell line, namely, RLT-PSC cells (established from tissue obtained from a chronic pancreatitis tissue resection), our results strongly suggest that TRPM7 is a marker of human pancreatic stellate cell activation." (PMID 35883700, 2022). "We then wondered whether TRPM7 could be actually a marker of human pancreatic stellate cell activation by measuring expression levels in another pancreatic stellate cell line, named RLT-PSC, isolated from patients with chronic pancreatitis." (PMID 35883700, 2022).
endothelial dysfunction (3 papers, 2013 to 2023). In vascular diseases, endothelial dysfunction is a systemic pathological state of the endothelium (the inner lining of blood vessels) and can be broadly defined as an imbalance between vasodilating and vasoconstricting substances produced by (or acting on) the endothelium. "Because low Mg promotes endothelial dysfunction partly through the action of free radicals, we propose TRPM7 overexpression as a potential marker of macrovascular endothelial dysfunction." (PMID 23533657, 2013). "Notably, increased TRPM7 expression was reported in aortas from MgL mice, a model in which endothelial dysfunction is detected." (PMID 23533657, 2013). "Moreover, high extracellular magnesium decreases the levels of TRPM7 by activating calpains, while low extracellular magnesium, known to promote endothelial dysfunction, stimulates TRPM7 accumulation partly through the action of free radicals." (PMID 23533657, 2013).
fibrosis (3 papers, 2021 to 2023). the formation of excess fibrous connective tissue in an organ or tissue in a reparative or reactive process. "Expression of TGFβ1, IL-11 and IL-6, mediators involved in cardiovascular fibrosis and inflammation, were increased in hearts from TRPM7-deficient mice and aldosterone-salt treated WT mice." (PMID 35882956, 2022).
heart failure (3 papers, 2019 to 2025). Inability of the heart to pump blood at an adequate rate to meet tissue metabolic requirements. "TRPM7 is known to support normal cardiac function and participates in the pathomechanisms that precipitate heart failure when dysregulated, namely cardiac fibrosis." (PMID 34682454, 2021). "Although the role of Mg2+ in ME/CFS remains equivocal, dysregulation of TRPM7 and therefore cellular Mg2+ homeostasis with secondary Ca2+ signalling dysregulation in both the heart and vasculature may contribute to the development of cardiac failure in ME/CFS." (PMID 34682454, 2021). "Mechanotransduction and Heart Failure: Mechanosensitive TRP channels (e.g., TRPC6, TRPM7, TRPV4) are activated under pathological stretch, making them promising targets in heart failure." (PMID 40313873, 2025).